CRP (C-reactive protein)
Diseases named in the same sentence as CRP in open-access papers (continued):
Sharing a sentence is not in itself a finding about the gene and the disease.
gout (117 papers, 2012 to 2026). A condition characterized by painful swelling of the joints, which is caused by deposition of urate crystals. "Another study reported that 12 weeks of TC citrate supplementation in males with gout decreased CRP by 42% and was associated with fewer gout flare-ups." (PMID 39408358, 2024). "Others showed elevation of serum IL-37 in gout patients, particularly in the active tophaceous gout and its association with the levels of C- reactive protein (CRP) and pro-inflammatory cytokines." (PMID 37853488, 2023). "Based on these findings, PIP has the potential to be a prophylactic and therapeutic treatment for the management of the clinical manifestations of gout that are systemic and associated with CRP." (PMID 35400961, 2022). "Few studies are currently available that explore the association of joint size involvement and CRP response in gout or CPPD." (PMID 34063875, 2021). "In terms of laboratory tests, it was difficult to judge that hyperuricemia was caused by peripheral gout or new lesions, and that the elevation of C-reactive protein was caused by gout or infection." (PMID 31521158, 2019). "We also tested for an association of serum ferritin, CRP and serum urate with self-reported frequency of gout flares (per year)." (PMID 30111358, 2018). "In the one study of 957 older Italians free of renal disease or gout, having higher uric acid was associated with increased neutrophils, CRP, IL-1ra, IL-6, IL-18 and TNFα." (PMID 28786993, 2017). "Taken together, these results suggest that NLR, as a cost-effective and readily accessible inflammatory marker, outperforms CRP and UA, offering a more comprehensive and pathophysiologically relevant tool for risk stratification and inpatient gout recurrence surveillance in clinical practice." (PMID 41293160, 2025). "Additionally, elevated CRP levels correlate with elevated all-cause and cancer-specific mortality in patients with gout." (PMID 41377556, 2025). "Additionally, chronic inflammation and interleukin (IL)-1β pathways, as well as C-reactive protein, all of which are hallmarks of gout, may be associated with the pathogenesis of CVDs." (PMID 37680887, 2023). "Although some population-based studies exclude individuals with infections our results suggest that other kinds of inflammation associated with an increased CRP may affect calibre too, including coincidental gout, inflammatory arthritis, skin rashes, and surgery." (PMID 34446820, 2021). "It outperformed serum uric acid (UA) and C-reactive protein (CRP) in predicting inpatient gout recurrence (AUC: 0.62 vs. 0.59 and 0.61, respectively), with improved accuracy when combined with UA (AUC = 0.65, P < 0.01)." (PMID 41293160, 2025). "Risk stratification showed that patients with both elevated NLR and CRP had the highest inpatient gout recurrence rates, followed by those with elevated NLR alone." (PMID 41293160, 2025). "ROC curves were performed to compare the predictive ability of NLR, UA, and CRP for inpatient gout recurrence." (PMID 41293160, 2025). "As expected, both gout and RA patients had higher C-reactive protein (CRP) concentrations as compared to controls, while gout patients had significantly higher uric acid concentrations compared to the two other groups." (PMID 40266325, 2025).
gout (continued). "This indicates that NLR can serve as a convenient adjunct for early risk stratification when conventional biochemical markers such as uric acid or CRP fail to fully capture inflammatory activity or inpatient gout recurrence tendency." (PMID 41293160, 2025). "CRP levels were markedly elevated in the acute gout attack group, while intercritical gout patients had intermediate values." (PMID 40722837, 2025). "We further compared the performance of NLR with CRP and UA in predicting inpatient gout recurrence, revealing that the AUC of NLR surpassed that of CRP and UA." (PMID 41293160, 2025). "The optimal cut-off values of disease duration, CRP and fibrinogen in distinguishing the presence of tophus in gout patients were 42 months, 20.65 mg/ml and 4.625 mmol/L, respectively." (PMID 38240927, 2024). "Extensive research has confirmed that TCM effectively alleviates joint pain and swelling while reducing levels of erythrocyte sedimentation rate, C-reactive protein, and serum uric acid during gout flares." (PMID 39130631, 2024). "In gout, CRP opsonizes MSU crystals, thus activating the classical and lectin pathway of the complement system by recruitment of C1." (PMID 38255787, 2024). "The results showed that three of them, including disease duration, CRP and fibrinogen, had moderate predictive performances for tophus in gout." (PMID 38240927, 2024). "Sour cherry juice provides several health benefits, such as anti-inflammatory and anti-gout, and has been claimed to be effective in decreasing CRP (C-reactive protein) and oxidative stress." (PMID 38891319, 2024). "Prior investigations reported that MSU-triggered inflammation induces gout formation, whereas PA promotes anti-inflammatory activities that diminish IL-6, C-reactive protein, and TNF." (PMID 39060811, 2024). "Previous study demonstrated that the CRP level of gout patients is significantly higher than asymptomatic hyperuricemia patients, which is one of the most widely used inflammatory markers." (PMID 38678252, 2024). "ROC analysis showed that disease duration, CRP and fibrinogen, had moderate predictive performances for tophus in gout (the AUCs were 0.753, 0.703 and 0.701, respectively)." (PMID 38240927, 2024). "Not only back pain and related CRP data, but also evidence on CRP and gout again seem conflicting in various studies, with hsCRP >9 mg/L possibly being associated with the pathogenesis of the disease." (PMID 37873776, 2023). "Significantly higher levels of plasma biomarker of systemic inflammation, CRP and sTNFR1 was noted in patients with gout (p = 0.008 & 0.022, respectively) and RA (p = 0.037 & 0.012, respectively) as compared to OA." (PMID 37202736, 2023). "HDL-C level was significantly lower in the gout group than in the control group (t = 14.33, P<0.001), whereas the TG, AST, ALT, and hs-CRP levels were significantly higher in the gout group." (PMID 38060535, 2023). "In line with the acute phase reaction during the gout attack, the median C-reactive protein (CRP) levels gradually increased toward the acute gout episode (p < 0.001)." (PMID 35237621, 2022). "Previous studies have shown that patients with gout had a higher intake of energy, protein, and alcohol, and had higher serum levels of vitamin B12, C-reactive protein, TG, and SU." (PMID 35628869, 2022). "C-reactive protein (CRP) is usually increased during a gout flare and can be quite high, although a high CRP alone is nonspecific." (PMID 36346841, 2022). "It remains to be seen if CRP or human IgM also alter crystallization of urates, the prerequisite for the development of gout." (PMID 35296708, 2022). "As an acute phase protein, CRP concentration in the blood strongly increases during inflammation, e.g., during gout flares." (PMID 35296708, 2022). "Gout attacks are often accompanied by a systemic inflammatory response, such as fever, where CRP is known to play a role in the manifestation of systemic symptoms of gout arthritis." (PMID 35400961, 2022).
gout (continued). "The AUC values of lymphocytes, sUA, and CRP for normal sUA gout patients were 0.694, 0.643, and 0.700, respectively, which were higher than those of other variables." (PMID 34567284, 2021). "A study from 1987 linked increased joint involvement to an increased CRP response in gout, while a more recent study was able to link a higher joint burden to an increased CRP reaction in female OA patients." (PMID 34063875, 2021). "Serum IL-18, an inflammasome-related cytokine, was reported to be higher in gout patients, and the serum IL-18 level was correlated with the level of C-reactive protein (CRP) and the erythrocyte sedimentation rate (ESR)." (PMID 34830282, 2021). "The ESR and CRP levels of gout, RA, and axSpA patients were higher than those of OA patients (P < 0.05)." (PMID 34567284, 2021). "The results showed that the AUC values of lymphocytes, sUA, and CRP for normal sUA gout were 0.694 (95% CI: 0.609–0.779), 0.643 (95% CI: 0.553–0.733), and 0.700 (95% CI: 0.619–0.781), respectively, which were higher than those of the other variables." (PMID 34567284, 2021). "The ROC curve results showed that the AUCs of lymphocytes, sUA, and CRP for normal sUA gout patients were 0.694, 0.643, and 0.700, respectively, which were higher than those of RA, axSpA, and OA patients." (PMID 34567284, 2021). "Calprotectin levels correlated with VAS disease activity (β = 0.31, p = 0.01), duration of morning stiffness in patients with poly-articular gout (β = 0.71, p < 0.01), and inflammation marker CRP (β = 0.23, p = 0.05)." (PMID 32552822, 2020). "Physically active gout patients had significantly less flares/yr, decreased C-reactive protein (CRP) levels, and lower pain scores relative to physically inactive patients." (PMID 33002030, 2020). "sUA levels positively correlated with BMI, ALT, TB, BUN, serum creatine, TG, CRP in gout group and negatively correlated with age and HDL-C (p < 0.05)." (PMID 32127000, 2020). "In concordance, physically active gout patients had significantly less flares/yr, decreased C-reactive protein (CRP) levels, and lower pain scores." (PMID 33002030, 2020). "Although a protective role of IL-33 in the kidney injury of gout was observed, we here found a positive correlation between the increased IL-33 expression and inflammatory indicator CRP (r = 0.38, p = 0.005)." (PMID 30863362, 2019). "A 39-year-old man with a recurrent episode of gouty arthritis presented prednisolone-resistant polyarthritis with high level of C-reactive protein (CRP)." (PMID 31577714, 2019). "In general, methods using the Gaffo CART-defined flare were more strongly correlated with other measures of gout activity compared with methods using self-reported flares, particularly with C-reactive protein." (PMID 31334482, 2019). "In this study, we found an increased level of IL-33 in gout patients, which was positively correlated with inflammatory marker CRP." (PMID 30863362, 2019). "In this study, an increased IL-33 expression was observed in gout patients, which was positively correlated with inflammatory marker CRP." (PMID 30863362, 2019). "CRP was an acute time-phase reaction protein and the most common inflammatory marker for disease activity index in acute gout." (PMID 30863362, 2019). "RA and other inflammatory arthritides (e.g. psoriatic arthritis, gout) comprised the largest percentage of subjects with CRP in the highest decile (34%), followed by infection (22%)." (PMID 29855349, 2018). "The assay of C-reactive protein (CRP) and determining the speed of sedimentation (SS) would have been required in the characterization of inflammatory reactions, for the deduction of a gout." (PMID 29518007, 2018).
gout (continued). "An increased risk of incident MI in people with gout raises a question regarding the role of chronic inflammation and IL-1β pathways (via NLRP3 inflammasome activation) and CRP, hallmarks of gout, in the pathogenesis of MI." (PMID 29859125, 2018). "Rilonacept, a soluble IL-1 receptor-Fc fusion protein, was evaluated in 10 refractory gout patients, resulting in decrease of pain and C-reactive protein." (PMID 23304159, 2012). "Similarly, SIRI was positively correlated with CRP in patients with gouty arthritis, and both SIRI and CRR had high diagnostic efficacy for gouty arthritis." (PMID 41509129, 2026). "In contrast, patients with low NLR had lower inpatient gout recurrence risk regardless of CRP status (P < 0.01 for all comparisons)." (PMID 41293160, 2025). "The AUCs for disease duration, CRP and fibrinogen in distinguishing tophus in gout were 0.753 (sensitivity of 0.923, specificity of 0.558, p = 0.003), 0.703 (sensitivity of 0.769, specificity of 0.681, p = 0.017) and 0.701 (sensitivity of 0.615, specificity of 0.770, p = 0.018)." (PMID 38240927, 2024). "Physical activity may exert anti-inflammatory effects by lowering IL-6, reducing C-reactive protein, and inhibiting TNF-α, thereby reducing the risk of gout." (PMID 38276301, 2024). "Another study indicated that oxidative stress and inflammatory markers including tumor necrosis factor, CRP, interleukin (IL) 1β, IL-6 may affect the development and clinical manifestations of gout based on hierarchical cluster analysis." (PMID 38678252, 2024). "The ROC curves showed that disease duration, CRP and fibrinogen had moderate predictive performances for tophus in gout, which indicated that tophus was chronic inflammatory tissue response and mostly the result of chronic recurrent gout attacks." (PMID 38240927, 2024). "CRP elevation reflects inflammation from potentially diverse sources of gout." (PMID 37679816, 2023). "In the other study, the chronic GA patients with a serum CRP level > 3 mg/dL who did not take prophylaxis were associated with gout flare recurrence during initial ULT therapy." (PMID 36609359, 2023). "However, the TaCCi mixture group demonstrated greater improvement in UACR and CRP compared to the other two groups, and fewer gout flares than the sodium bicarbonate group." (PMID 37679816, 2023). "The univariate logistic regression analysis demonstrated that there was a significant association between abnormal VPT and age, duration of gout, SBP, C-reactive protein, ESR, presence of tophi, and estimated glomerular filtration rate (eGFR) in all the subjects (P < 0.05)." (PMID 35280274, 2022). "Therefore, PIP is capable of disrupting the NLRP3 inflammasome and has the potential to inhibit CRP production during the acute phase of gout inflammation." (PMID 35400961, 2022). "Modified Simiao decoction (MSD) monotherapy is superior to anti-inflammatory drugs and/or uric acid-lowering drugs in treating gouty arthritis, and it can reduce uric acid (UA) and C-reactive protein (CRP) levels; regulate human metabolic disorders; and has no side effects." (PMID 34721646, 2021). "Blood tests may show elevation of the erythrocyte sedimentation rate (ESR) or C-reactive protein (CRP) during a gout flare." (PMID 35011907, 2021). "A recent study reported the identification of CRP as a genuine MSU crystal recognition molecule, and speculated that CRP binding to MSU crystals modulates gout associated inflammation." (PMID 33154749, 2020). "Considering the improved gout patient clinical course and CRP levels observed in our human cohort and the increasing prevalence and incidence of gout, this further highlights the importance of incorporating low or moderate-intensity exercise as an adjunct treatment option." (PMID 33002030, 2020). "In our study, we found that the expression of IL-33 in gout patients was significantly higher than that of the healthy control group, which was positively correlated with inflammatory indicator C-reactive protein (CRP)." (PMID 30863362, 2019).
gout (continued). "Although the time-dependent methods of reporting had generally good concurrent validity in groups with different baseline gout characteristics, we did observe higher correlations with C-reactive protein in those with tophi, longer diseae duration and more frequent flares." (PMID 31334482, 2019). "The mean CRP was elevated in all groups but was significantly higher in gout patients." (PMID 26198435, 2015). "PCT was significantly positively correlated with VAS, CRP and ESR in gouty arthritis and CRP in AS." (PMID 26182343, 2015). "Moreover, disease duration, CRP and fibrinogen can predict the presence of tophus in gout." (PMID 38240927, 2024). "However, the TaCCi mixture resulted in greater improvements in UACR and CRP, which suggests that tart cherry supplements may provide additional benefits for renal protection and reduce inflammation in gout, particularly when starting ULT." (PMID 37679816, 2023). "Regarding the inflammatory indicators, there was a significant increase in the levels of CRP (38.12 ± 48.46 vs. 7.55 ± 9.82, p = 0.014), IL-1β (55.92 ± 45.54 vs. 41.86 ± 32.42, p = 0.028) and IL-6 (45.89 ± 96.51 vs. 8.75 ± 6.43, p = 0.031) when the patient had an acute gout flare." (PMID 36896178, 2023). "Besides activation of the complement system, binding of CRP or IgM to crystals may alter gout pathophysiology also by other mechanisms." (PMID 35296708, 2022). "Furthermore, the levels of IL-22 and VD3 correlated with that of CRP in gout patients." (PMID 34917427, 2021). "In addition, ERS and CRP are important indicators for clinical evaluation of gout symptoms." (PMID 33205687, 2020). "Moreover, we found higher levels of CRP in gout patients than in the control group." (PMID 30621105, 2019). "Interestingly, in our present study, although the level of IL-33 expression was increased in the gout patients and positively correlated with inflammatory marker CRP, the exogenous IL-33 treatment significantly inhibited the development of inflammation induced by MSU administration." (PMID 30863362, 2019). "The proportions of MDSCs and M-MDSCs were correlated with CRP in RA patients (r=0.379, 0.594; p=0.036, p<0.001), AS patients (r=0.494, 0.801; p=0.023, p<0.001), OA patients (r=0.877, 0.746; p<0.001, p=0.002), and Gout patients (r=0.762, 0.883; p=0.017, p=0.002)." (PMID 30046600, 2018). "At three-month follow-up, the patient remained free of gout recurrence, with VAS 1, CRP 7.8 mg/L, and UA 393 μmol/L." (PMID 42239734, 2026). "Classic inflammatory markers, such as CRP, WBC, NEU, and ESR, were significantly elevated in patients experiencing acute gout attacks." (PMID 40722837, 2025). "ESR, CRP, WBC, GR, Mo, and LY serve as inflammation-related indicators crucial for assessing disease activity in gouty arthritis." (PMID 40170729, 2025). "The predictive importance of NLR was comparable to predictors including UA and CRP, a finding that was validated in the MIMIC-IV cohort, further supporting the robustness of NLR as a significant predictor of inpatient gout recurrence." (PMID 41293160, 2025). "In the present study, the IL-6 levels were elevated in gout patients, and positively related to ESR, CRP, D-dimer, fibrinogen, neutrophils and monocytes." (PMID 38240927, 2024). "Elevations in serum acute phase proteins, including C-reactive protein (CRP) and erythrocyte sedimentation rate (ESR), occur in patients with acute gout flare." (PMID 36609359, 2023). "The C-reactive protein (CRP) and erythrocyte sedimentation rate (ESR) levels of gout were higher than OA." (PMID 35359923, 2022). "Hence, gout flares in patients may resemble septic arthritis (fever, high CRP)." (PMID 33154749, 2020). "The controls had lower weight, BMI, CRP levels, LDL-C levels and TG levels than the gout patients (p < 0.05)." (PMID 30621105, 2019). "C-reactive protein (CRP) is an acute phase and inflammatory marker for the disease activity index in patients with gout." (PMID 31312662, 2019).